IL6 (interleukin 6)
Diseases named in the same sentence as IL6 in open-access papers (continued):
Sharing a sentence is not in itself a finding about the gene and the disease.
cancer (continued). "Along the same line, increased circulating levels of tumor necrosis factor α (TNFα), interleukin-6 (IL-6), γ-interferon (INF), and, more recently, growth and differentiation factor 15 (GDF15) have been reported in cachectic cancer patients." (PMID 29785246, 2018). "Adipocytes secrete adipokines (LEP, ADIPOQ, IL-6, IL−1β, TNFα), MMPs, and PAI-1, to enhance cancer progression." (PMID 29881724, 2018). "IL-6 accelerates EMT through an altered expression of N-cadherin, E-cadherin, twist, snail, and vimentin, which results in cancer metastasis." (PMID 29770167, 2018). "For example, mounting evidence suggests a crosstalk between IL-6 and MDR in cancer and potential therapeutic opportunities arising from this role of IL-6." (PMID 29946544, 2018). "Within the brain, cytokines including IL-6 and TNF-α are typically tasked with promoting neurogenesis and offering neural trophic support; however, overactive immune pathways seen in cancer are thought to lead to dysregulation of these processes." (PMID 30042700, 2018). "Interestingly, ERα-negative breast cancer have high basal secretion of the cytokines interleukin (IL)-8 and IL-6, which have been linked to the pathophysiology of cancer, suggesting that ERα-negative breast cancer secretes cancerogenic, CSC- and growth-promoting cytokines including progranulin." (PMID 30454027, 2018). "A previous study has shown that telomerase is bound to the promoters of a subset of NF-κB target genes, including IL6, IL8, and TNF-α and stimulate their expression to sustain inflammation and promote cancer progression." (PMID 29986697, 2018). "In the present study, we found that Wwox affects the IL-6/JAK2/STAT3 (interleukin-6/Janus kinase-2/signal transducer and activator of transcription-3) axis, inhibiting cancer cell growth and metastasis in a STAT3-dependent manner." (PMID 30154439, 2018). "CSCs also elevated secretion of IL-6, RANTES and MCP-1, all of which promoted inflammation, attracted inflammatory cell infiltration and contributed to cancer progression." (PMID 30486830, 2018). "Inflammatory cytokines IL-1 and IL-6 also modulate pro-oncogenic transcription factor STAT3, thereby increasing survival, proliferation, angiogenesis, invasion, and metastasis of cancer cells." (PMID 29370858, 2018). "With regard to cancer, a study using a mouse model of OSCC revealed that CD147 inhibition resulted in decreased inflammatory mediators, such as IL-6 along with reduced collagen degradation and cell growth in vitro." (PMID 30248985, 2018). "IL-6 has been reported to enhance angiogenesis via the STAT3 pathway to act as a growth factor and to be involved in chemoresistance in cancers." (PMID 29486738, 2018). "Distribution of clinical–pathological characteristics, in cancer sorted according to indoleamine 2,3-dioxygenase (IDO) or interleukin (IL)-6 gene expression levels." (PMID 29896191, 2018). "Remarkably, IL-6, IL-10, CXCR4, and CCL2 mRNA, which are all STAT3 target genes involved in cancer progression, were increased in macrophages exposed to exosomes." (PMID 29867925, 2018). "Both cancer cell lines and live mf significantly (p = 0.001) upregulated the production of IP-10 and CCL22, while IL-6 production was significantly upregulated only by cancer cell lines and not by mf." (PMID 29668679, 2018). "We systematically analyzed MUC2 and IL-6 expression and determined the survival of cancer patients with high or low MUC2 and IL-6 expression using the Oncomine and PrognoScan databases, respectively." (PMID 28725043, 2017). "The identified downstream targets of miR-365 include cell division cycle 25A (CDC25A), cyclin D1 (CCND1), transcription termination factor 1 (TTF1), interleukin 6 (IL-6) and nuclear factor I B (NFIB) in various types of cancers." (PMID 28556798, 2017). "Cancer cells produce many pro-inflammatory cytokines and chemokines such as GCSF, IL-1 and IL-6, but they are also actively involved in cytotoxic T-cell and natural killer cell suppression." (PMID 28473700, 2017).
cancer (continued). "Overall, these data support a role for BET proteins in modulating circulating IL6 and PTHrP levels and suggest that the BET inhibitor (+)-JQ1 restrains cancer cachexia through the reduction of IL6 and other cachectic factors." (PMID 29167426, 2017). "As the downstream of IL-6/GP130, phosphorylation of STAT3, as well as STAT3 downstream target genes, were inhibited by Raloxifene in Hep-G2, Huh-7 and 7721 cancer cell-lines." (PMID 28430601, 2017). "TAMs accordingly produce multiple growth factors (HGF, EGF, TGF, PDGF, etc.)and inflammatory cytokines (IL‐1β, IL‐6, and TNF‐α) that each can induce EMT in cancer cells." (PMID 28599100, 2017). "Given that IL-6 can activate downstream STAT3, a key oncogene constitutively activated in many cancer including HCCs and contributing to cancer cell proliferation and survival, we examined hepatic STAT3 activation in both genotypes 10-month post DEN injection." (PMID 28036277, 2017). "In particular, we evaluated the effects of treatment with Ganoderma lucidum on the release of IL-6, IL-8, MMP-2 and MMP-9 and other inflammatory cytokines promoting cancer." (PMID 28264501, 2017). "Neuroinflammation in the context of cancer and cancer-treatment is frequently characterized by changes in expression of proinflammatory cytokines such as IL- 1β, IFN-γ IL-6, and TNF-α." (PMID 27893434, 2017). "Our study showed that doxycycline suppressed both LPA- and TNFα-induced nuclear translocation of NF-κB and blocked the LPA-induced secretion of IL-6, CCL2 and CXCL2 in cancer cells." (PMID 28178994, 2017). "Strong MUC2 expression and low IL-6 and CD68 expression were detected in the same specimen from a patient with stage IIA cancer (upper left and upper right)." (PMID 28725043, 2017). "Therefore we quantified the amount of some pro-inflammatory cytokines (IL1β, TNFα, IL12-p70, IL6, IL8, IL10) by CBA and found that the SCM was highly enriched in IL6 and IL8, two pleiotropic pro-inflammatory cytokines that have been implicated in cancer progression." (PMID 28472950, 2017). "High serum levels of IL6 and IL8 in patients with cancer are assumed to be derived from strong local secretion from tumors." (PMID 28903357, 2017). "Our study demonstrates, for the first time, how Ganoderma lucidum extracts can significantly inhibit the release of IL-8, IL-6, MMP-2 and MMP-9 in cancer cells under pro-inflammatory condition." (PMID 28264501, 2017). "Neutralizing antibodies to IL-6 or histone H3 or knockout of RAGE all limit K-Ras signaling activation, prevent cancer development and metastasis/invasion, and prolong animal survival in KCH mice." (PMID 28374746, 2017). "Many previously published studies have revealed that n-3 PUFAs can down-regulate the levels of IL-6 and TNF-α in cancer patients postoperatively." (PMID 28410575, 2017). "Inflammatory cytokines derived from cancer cells and host immune cells, including interleukin (IL)-1, IL-6, tumor necrosis factor (TNF)-α, and leukemia inhibitory factor (LIF), are involved in the development of cancer anorexia-cachexia." (PMID 28249026, 2017). "It has been reported, that IL-6-induced activation of the PI3K/AKT pathway is involved in protection against apoptosis, as well as in enhanced proliferation in some cancer cells." (PMID 28903416, 2017). "There are reports shown that fibroblasts involve in the cross-talk of cancer cells and fibroblasts by secreting CCL2, CCL5, CXCL1, CXCL6, CXCL12, IL6, CXCL16 and others." (PMID 28465475, 2017). "Cancer biomarker prostate-specific antigen capture antibodies (PSA-Ab1) and interleukin-6 capture antibodies (IL-6-Ab1) were covalently coupled onto the SWNTs forest for capturing protein analytes." (PMID 30393720, 2017). "In fact, the IL-6/JAK/STAT3 signaling pathway is “druggable” at various levels and clinical trials for different cancer entities are ongoing (see clinicaltrials.gov)." (PMID 28895886, 2017).
cancer (continued). "Cancer cells suppress the functions of effector T cells by producing immunosuppressor cytokines TGF- β, IL-6, CCL2 and IL-10." (PMID 28724377, 2017). "IL-6 and TNF-α are two proinflammatory cytokines that well recognized to have close relationship with promotion and progression of cancer." (PMID 29100404, 2017). "The negative regulator SOCS3 is a key player in the modulation of the JAK/STAT signaling that control a number of inflammatory cytokines such as IL6 and IL16 and is involved in infectious diseases and cancers." (PMID 28179578, 2017). "Proinflammatory cytokines IL-6, TNF-α, and TGF-β have been widely examined for their regulation of cancer cachexia." (PMID 28785374, 2017). "Several lines of evidence have demonstrated that key molecules that are involved in cancer-related inflammation include NF-kB, STAT3, and major inflammatory cytokines, such as IL-1b, IL-6, IL-23, and TNF-a." (PMID 29232409, 2017). "The robust expression of IL-6, IGFBP-3, and serpinE1 following coculture with obASCs would suggest that these cancer cells are more aggressive." (PMID 29527228, 2017). "Anti-IL-6 drugs have been developed and already used for treatment of various diseases and cancers, such as CNTO328 chimeric anti-IL-6 monoclonal antibody (mAb) (siltuximab) and anti-IL-6R mAb, atlizumab (also called tocilizumab)." (PMID 29163240, 2017). "IL-6/STAT3 signaling can effectively trigger EMT action and expand the cancer stem cells population in several types of tumors." (PMID 29383101, 2017). "Upregulation of IL-6 and activation of STAT3 autocrine pathway have been shown to account for the major mechanisms of cancer cell resistance to therapy." (PMID 28077171, 2017). "IL-6 is a pro-inflammatory cytokine regulated by TLR3 and has been shown to be important for the growth and migration of cancer cells." (PMID 29371911, 2017). "Seven cofactors (TFAP2A, E2F, GSTM1, IL6, PATZ1, MEF2A and GTF2I) identified in two of the five cancer types have general functions in cancers." (PMID 28684851, 2017). "IL-6 secreted by CAFs mediates EMT and contributes to platinum resistance in NSCLC cell lines and isolated cancer cells of NSCLC patients." (PMID 28402937, 2017). "IL-6 secreted in the TME has been suggested to promote development and progression of certain cancers by driving progression and EMT." (PMID 28445977, 2017). "Our experiments showed that IL-6 treatment induced STAT3 and Chk2 activation and attenuated CREB/ATF-1 phosphorylation in MUC2-silenced HT-29 cancer cells." (PMID 28725043, 2017). "Activation of macrophages through their TLR2/4 leads to the release of cytokines such as IL-6 and TNF-α to adjacent cancer cells." (PMID 28969049, 2017). "For example, it was recently reported that some CAFs and pre-cancerous hepatocytes recruit MDSCs via IL-6 and CCL2-mediated pathway, respectively, thereby protecting cancer cells from immune cells." (PMID 29234059, 2017). "In particular, activation of STAT3 leads to expression of interleukin-6 and COX-2 which mediate cancer-promoting immunity." (PMID 28881698, 2017). "IL-6 is mainly produced by activated T cells and fibroblasts, and it induces EMT in many types of cancer cells." (PMID 29100297, 2017). "Several inflammatory mediators, such as IL-6 and TGF-β, have been shown to participate in both the initiation and progression of cancer." (PMID 29029413, 2017).
cancer (continued). "The induction of IL-6 secretion and subsequent autocrine/paracrine activation of STAT3 signaling supports the self-renewal activity of not only cancer cells but also embryonic stem cells or induced pluripotent stem cells." (PMID 28099924, 2017). "The IL-6/STAT3 signaling pathway plays an important role in the regulation of stemness, EMT, and metastatic dissemination of cancer cells." (PMID 29228728, 2017). "The mechanism is promoted by an S1P/S1P1-dependent increase in signal transducer and activator of transcription 3 (STAT3) and IL-6 formation; this S1P1 dependent pro-inflammatory pathway was first, demonstrated in cancer cells." (PMID 28241498, 2017). "We recently reported that IL-27, a heterodimer cytokine related to both IL-6 and IL-12 cytokine families, has several functional activities in common with IFN-γ, in different cancer cells." (PMID 29020964, 2017). "It is well known that NF-κB plays a critical role in inflammation and is a transcription factor for a number of immune-related genes (IL-6, CCL2, among others) involved in immune responses; thus, it plays a dual role in promoting and inhibiting cancer." (PMID 29312296, 2017). "CPD induces the expressions of several factors, such as C-C chemokine ligand (CCL) 2, IL-6, and VEGF-A, in bone marrow to create a pro-metastatic microenvironment for cancer cells and osteoclast to survive and the suppressed expression of MSCs in bone marrow." (PMID 29228681, 2017). "IL‐6 secreted by cancer cells activates STAT3, and induces downstream events, including cancer cell proliferation and apoptosis inhibition." (PMID 28618162, 2017). "The expression and prognostic value of IL6 and the IL6 receptor (IL6R) were explored in The Cancer Genome Atlas (TCGA) and REMBRANDT databases and clinical samples." (PMID 29258522, 2017). "Once cancer cells have migrated to bone, various growth factors, i.e. VEGF and cytokines including IL-6, are secreted and induce osteolytic activity." (PMID 28496132, 2017). "Core SASP factors such as IL-6 can mimic the effects of in vivo reprogramming, thereby favoring the emergence of CSC-like cellular states in neighboring cancer cells." (PMID 28529938, 2017). "It has been observed that CAFs actively communicate with cancer cells through growth factors or inflammatory cytokines such as HGF, IL-6, TGF-β, VEGF, FGF, and CXCL12 that can promote tumorigenesis and progression." (PMID 28186964, 2017). "To further examine the impact of Oligo-Fucoidan on IL-6 and CCL2 secretion from cancer cells, we treated HCT116 cells with etoposide and Oligo-Fucoidan (400 μg/ml) or etoposide alone for 24 h before incubating the cells in serum-free media for another 48 h." (PMID 28928376, 2017). "The model includes dendritic and cancer cells, CD 4+ and CD 8+ T cells, MDSC cells, interleukins IL-12, IL-2, IL-6, IL-10 and TGF- β, PD-1 and PD-L1, and the two drugs: BRAF/MEK inhibitor (with concentration γB) and PD-1 inhibitor (with concentration γA)." (PMID 28724377, 2017). "The presence of chronic inflammation in cancer patients has been held responsible for the induction of MDSC via growth factors and cytokines (e.g. G- or GM-CSF, IL-6, TGFβ, PGE2) acting via ERK/mTOR, STAT, NFκB and SMAD signaling pathways." (PMID 28978044, 2017). "Microfluidic immunosensors for several cancer biomarkers, such as PSA and interleukin-6 (IL-6), were prepared by immobilizing the corresponding antibodies on the AuNPs." (PMID 28672780, 2017). "IL-6 and its downstream molecules, such as STAT3, play an essential role in inflammation, aberrant immunity, and also carcinogenesis in some carcinomas." (PMID 28507278, 2017). "The serum levels of IL6 and IL8 in patients with BM of breast, lung and undefined carcinoma were significantly higher than those in healthy controls (p=0.0335 and p=0.0472, respectively)." (PMID 28903357, 2017).
cancer (continued). "We focused on IL-1β, IL-6, and TGF-β1 because these are well-known cancer progression-related factors for many malignancy types, including bladder cancer." (PMID 27698389, 2016). "Inflammatory cytokine levels such as those of IL-6 and TNF-α were significantly increased in KRAS-induced ascites, suggesting that inflammation plays a central role in KRAS-induced cancer progression." (PMID 27483433, 2016). "In cancers, the main mechanisms involved in STAT3 activation are IL-6 autocrine synthesis and IL-6 paracrine activation from the stroma and infiltrating inflammatory-associated immune cells." (PMID 26745884, 2016). "Our results demonstrated that in the presence of ionizing radiation either RKO or SW1463 cancer cells increased mRNA expression levels of the macrophage pro-inflammatory markers TNF, IL6, CCL2 and CCR7 as well as of the anti-inflammatory marker CCL18." (PMID 27513864, 2016). "IL-6 overexpression is indicative of inferior survival outcomes in patients with NSCLC, and it is related to the acute phase response and cancer cachexia." (PMID 27445423, 2016). "In our mouse model of TNBC, radiation stimulates the cancer cell migration and development of metastasis which seems to involve multiple inflammatory pathways including those of COX-2, IL-1β and IL-6." (PMID 27282478, 2016). "The positive feedback loop of two key inflammatory signaling pathways, NF-kB and IL-6/STAT3, has been suggested as a link between inflammation and cancer in previous studies." (PMID 27609180, 2016). "IL-6 induces STAT3 activation, and persistently activated STAT3 promotes the proliferation and metastasis of many cancers." (PMID 26623559, 2016). "Blockade of IL-6 reduced TAF-stimulated DCIS growth and proliferation and reduced the formation of TAF–cancer cell interconnections." (PMID 27515302, 2016). "More recently, it has been demonstrated that MSCs interact with cancer stem cells (CSC) in human cancer and regulate their self-renewing capacity through cytokine networks involving IL-6 and CXCL7." (PMID 27084089, 2016). "The marked difference in OS for high versus low IL-6 or CRP despite relatively small differences in PFS is consistent with data indicating a special role of inflammation in advanced and cachectic cancer." (PMID 27738330, 2016). "We identify interleukin-6 as a SOM230-inhibited CAF-secreted effector, which stimulates cancer cell features through phosphoinositide 3-kinase activation." (PMID 27177087, 2016). "Proinflammatory cytokines interleukin 1 beta (IL-1β), interleukin 6 (IL-6) and tumor necrosis factor alpha (TNF-α) regulates inflammatory response and play significant role in the development of cancer." (PMID 27034760, 2016). "Different genes involved in cancer progression of pro-angiogenic cytokines (VEGF) and of IL-6 and IL-8 were also down-regulated." (PMID 27171110, 2016). "Furthermore, the interactions between cancer cells and the surrounding microenvironment, as well as their secreted cytokines and growth factors (for example, IL-6 and stromal cell-derived factor 1), and altering the ECM may also play key roles to development of docetaxel resistance." (PMID 26625310, 2016). "Much like AMPK, muscle-derived IL-6 works as a sensor of energy “status,” ultimately leading to glucose uptake, lowering of serum glucose levels, and lipid oxidation, all changes that improve global metabolic function and may synergize with cancer treatment with chemotherapy and RT." (PMID 26977321, 2016). "CAF or TAM secretes IL-6, which induces cancer EMT (epithelial-mesenchymal transition) or an immunosuppressive condition, thereby contributing to cancer progression." (PMID 27483433, 2016).